IL6 (interleukin 6)
Diseases named in the same sentence as IL6 in open-access papers (continued):
Sharing a sentence is not in itself a finding about the gene and the disease.
liver disease (continued). "It has been shown that changes in the levels of biomarkers such as CRP, lymphocytes, neutrophils, and cytokines such as IL-6 can, in turn, lead to liver disorders." (PMID 36531832, 2022). "The proinflammatory cytokines IL-6 and IL-18 have critical roles in establishment of inflammation, and involved in the induction of liver diseases." (PMID 36311675, 2022). "Clinical and experimental data demonstrated that expression of the TNF-α and IL-6 genes are increased and positively correlated with the severity of the liver disease in human and animal models." (PMID 35806336, 2022). "In contrast, IL-6 has a less well defined role in the context of inflammatory liver disease, in that it has been ascribed both pro‐ and anti‐inflammatory activities." (PMID 33841403, 2021). "Various types of proinflammatory markers like TNF-alpha and IL-6 have been found to contribute to the pathogenesis of liver diseases." (PMID 33531877, 2021). "Previous studies provided some insights into the regulation mechanisms of GP73 expression via activation of the mammalian target of rapamycin (mTOR) pathway and inflammation-related factors such as Interleukin-6 (IL-6) in liver disease." (PMID 33540642, 2021). "Cirrhotic patients with advanced liver disease (MELD score of 20–29 or Child–Pugh C) had highly elevated IL-6 plasma levels compared with patients with initial or stable liver disease (MELD ≤ 9 and Child–Pugh A)." (PMID 33723292, 2021). "To understand the relevance of IL-6 in liver diseases, we initially performed a screening of existing literature, published between 2000 and 2021, reporting altered blood levels of IL-6 in HCC patients compared to those in healthy control." (PMID 35127527, 2021). "This places IL-6 at the crossroads of its conventionally believed hepato-protective role, compared to a cytokine involved in liver diseases." (PMID 35127527, 2021). "The median level of C-reactive protein (CRP) was higher in the hepatic disorder group, with a significantly higher concentration of IL-6, IL-10, and M-CSF." (PMID 32903864, 2020). "Although the hepatoprotective function of IL-6 has been fully demonstrated, the ubiquitous expression of IL-6 receptor makes many potential side effects of IL-6 in the treatment of liver diseases, which limits its clinical application." (PMID 32760208, 2020). "On admission, the levels of CRP and the production of the cytokines IL-6, IL-10, and M-CSF were significantly elevated in patients with a liver disorder." (PMID 32903864, 2020). "Further, C-reactive protein levels were much higher in the hepatic disorder group, with significantly higher concentrations of IL-6, IL-10, and M-CSF." (PMID 32903864, 2020). "Inflammatory burden is a primary cellular event in many liver diseases, and IL-6 is a major proinflammatory cytokines." (PMID 29234281, 2017). "The hepatocytes, Kupffer cells, and HSC secrete large quantities of IL-6 in the liver disease state." (PMID 28646179, 2017). "Taken together, these findings support that the role of IL-6 in liver disease varies greatly between humans and animals, and the direct relationships between IL-6 and HCC are still unclear." (PMID 27589954, 2016). "Several studies have shown a correlation between serum IL-6 concentration and the severity of HE in people with liver disease." (PMID 25658922, 2015). "Elevated serum IL-8 has been detected in BA infants with jaundice and/or portal hypertension, and the serum concentration of IL-6 has been found to correlate with the severity of BA." (PMID 26247025, 2015). "IL-6 acts as a proinflammatory cytokine; it can induce hepatic inflammation and has an important role in the pathogenesis of fibrosis and diseases of the liver." (PMID 24822223, 2014). "Cytokines such as IL-1β, TNF-α, IL-8 and IL-6 have been involved in chronic liver inflammation and pathogenesis of various liver diseases; among which IL-6 and TNF-α, are thought to be most important." (PMID 24918094, 2014).
liver disease (continued). "Hepatocytes bear a variety of cytokine receptors and the inflammatory cytokines IL-6, IFN-γ and TNF-α play pathogenic roles in liver disease." (PMID 23403509, 2013). "Considerable evidence suggested that TNF-α and IL-6 contribute to the pathogenesis of liver inflammatory diseases by activating the NF-κB signaling pathway." (PMID 23243434, 2012). "The hazards associated with increased IL-6 and risk of all-cause, cardiovascular, cancer, and liver-related mortality in older adults excluding individuals with prevalent CVD, cancer, and liver disease over 15 years of median follow-up." (PMID 22514624, 2012). "In liver disease, clinical data also indicate that serum IL-6 concentrations are elevated in patients with chronic liver inflammation, and steatohepatitis as well as in patients with HCC." (PMID 22136659, 2011). "During acute and chronic liver disease, the expression of IL-6 correlates with liver disease progression." (PMID 21394214, 2011). "We injected three mice with NPC1-specific antisense oligonucleotides (ASOs) twice a week for 15 weeks to induce NPC liver disease and found undetectable levels of IL-6 (<4 pg/ml)." (PMID 20886067, 2010). "Increased IL-6 levels during liver injury can promote liver regeneration and may influence bone remodeling in different liver diseases." (PMID 41601928, 2026). "IL-6/ceramide-induced lysosomal dysfunction may constitute a common lipotoxic pathology across liver diseases." (PMID 41256541, 2025). "To determine whether IL-6 levels correlate with liver disease severity, we systematically analyzed IL-6 concentrations across all seven non-invasive fibrosis scoring systems." (PMID 41590632, 2025). "However, on the other side, high IL-6 level produced by senescent cells can also lead to the reprogramming of hepatocytes, and performs its protective effect on the development of liver diseases with anti-inflammatory activities." (PMID 38890694, 2024). "First, its retrospective design might have introduced biases due to unmeasured confounding factors, such as liver disease, post-transplant status, solid and/or hematological malignances, and several biomarkers including IL-6 and tumor necrosis factor α." (PMID 39695439, 2024). "Additionally, Akkermansia decreases IL-6 levels and reduces triglyceride synthesis, mitigating lipid peroxidation in steatotic liver disease models." (PMID 39796579, 2024). "Therefore, the purpose of the current research is to investigate the role of IL-6 and TLR2 gene polymorphism in chronic active hepatitis B and how they affect the progression of HBV-associated liver disease (liver cirrhosis and HCC)." (PMID 39071840, 2024). "Additionally, local IL-6 level is decreased in early-stage human liver diseases as compared to healthy liver tissues, suggesting a protective role for local IL-6 in the healthy liver." (PMID 38890694, 2024). "Therefore, in order to more accurately intervene the IL-6-mediated liver diseases or aging, it is of prior importance to understand when, where, and how IL-6 works in the physiological and pathological processes in the liver." (PMID 38890694, 2024). "Notably, the dataset includes many known proteins (IL6, IL10, IFNG, CSF3, PDGFB, CD40, and AFP) and novel proteins associated with liver diseases." (PMID 37209815, 2023). "Hepatocytes regulate liver injury, repair, and inflammation in liver diseases by producing IL-6." (PMID 36788538, 2023). "Moreover, previous studies showed increased serum levels of interleukin 6 (IL-6) related to liver disease progression and found correlations of IL-6 levels with mortality." (PMID 35176084, 2022). "IL-6 could lead to excessive inflammatory activation that induces oxidative stress, followed by tissue damage and liver disease progression." (PMID 36498787, 2022).
liver disease (continued). "In liver disease, glucose metabolism shifts from the liver to muscle and adipose tissue, which stimulates mitochondrial oxidative stress and drives the production of proinflammatory adipokines, e.g., leptin, tumor necrosis factors-alpha and interleukin-6." (PMID 35743539, 2022). "The exposure to endotoxins activates macrophages via Toll-like receptor 4 (TLR4), leading to a greater production of proinflammatory cytokines and chemokines including tumor necrosis factor-alpha, interleukin (IL)-6, and IL-8, which play key roles in the progression of liver diseases." (PMID 34203178, 2021). "As IL-6 increases during liver injury to stimulate liver regeneration, upregulated IL-6 could affect bone remodeling in various types of liver disease." (PMID 33807573, 2021). "Notably, during liver disease, chronic inflammation, profound tissue remodeling, and genetic alterations result in the production of both pro-inflammatory (e.g., IL-6, TNF-α) and/or anti-inflammatory or immuno-suppressive (e.g., TGF-β, IL-10) cytokines." (PMID 35127527, 2021). "IL-6 is a proinflammatory cytokine typically upregulated in advanced liver disease." (PMID 32899730, 2020). "Furthermore, HCV infection has been shown to play an important role in development of liver disease via the IL-6/STAT3 pathway." (PMID 32266003, 2020). "Also, other studies did not consider concentration or duration of exposure of cells to IL-6 and the study by Hassan for example was in hepatic disorders." (PMID 31652937, 2019). "In addition, IL-1, IL-6, and IL-8 are also increased in common liver diseases, such as simple steatosis, NASH, and liver cirrhosis." (PMID 30158441, 2018). "IL-6 is a key cytokine of liver regeneration that is also elevated during liver disease." (PMID 28330461, 2017). "Portal hypertension leads to ascites and is positively correlated with serum IL-6." (PMID 28661458, 2017). "Liver disease was evaluated by biochemical analysis, IL6 measurement and histological assessment." (PMID 29019564, 2017). "In a preclinical model of liver disease, mice pretreated with IL-6 have less hepatic injury." (PMID 28661458, 2017). "For example, adequate levels of TNF and IL-6 are critical for liver regeneration; to inhibit all TNF or IL-6 activity in a patient with severe liver disease could potentially inhibit recovery." (PMID 15706742, 1997). "Clotting factor deficiencies may also be due to reduced synthesis for hepatic disease, increased clearance in enlarged spleen, or accelerated consumption in a state of low-grade intravascular coagulation and fibrinolysis, supported by IL-1α, TNF-α, and IL-6." (PMID 36498496, 2022). "Therefore, targeting IL-6 and its related signaling pathways in the liver could hint at a new target for the diagnosis and treatment of liver disease." (PMID 35455983, 2022). "In addition, LPS induces the secretion of a variety of inflammatory factors, such as TNF-α, IL-6, and TGF-β, which are involved in liver disease caused by LPS, especially in the end-stage liver disease, such as hepatitis B or C virus infection induced liver cancer." (PMID 35965618, 2022). "Besides, plasma IP-10 and IL-6 have also been correlated to advanced liver disease (CTP 7-9)." (PMID 33598470, 2021). "Interleukin 6 (IL-6), quickly produced in response to different infections and tissue injuries, attributes response to host defense through the stimulation of acute phase responses, hematopoiesis, and immune reactions, and its overexpression has been noticed in liver diseases." (PMID 33531877, 2021). "Indeed, the dysregulated synthesis of IL-6 activates downstream immune and oxidative stress signaling to exacerbate inflammation infiltration and eventually leads to the onset or development of liver diseases." (PMID 32266003, 2020). "Thus, IL-6 plays an important role in the pathology of liver diseases and ILC2 might contribute to IL-6-mediated hepatic immune regulation following activation by IL-33." (PMID 31974518, 2020).
liver disease (continued). "Previous researches have demonstrated that gut microbiota can modulate the release of IL-6, TNF-α, hepatocyte growth factor (HGF), IFN-γ and TGF-β, which are involved in liver regeneration and different liver disorders." (PMID 41333471, 2025). "In liver diseases, signaling pathways such as TLR4 and NF-κB activate endogenous cellular inflammatory vesicles, releasing pro-inflammatory cytokines like IL-1β, IL-6, and TNF-α." (PMID 39936090, 2025). "Elevated circulating levels of inflammatory cytokines, including interleukin IL-6, IL-1, and TNF-α, can be found in liver disease." (PMID 40430241, 2025). "IL-6 levels were markedly elevated in ACLF EF+ patients, who exhibited the highest median concentrations among all liver disease phenotypes IL-6 levels in ACLF EF+ patients were significantly higher than those in SDC EF+ patients (p≤ 0.05)." (PMID 41189884, 2025). "IL-6 is a mediator as well as a biomarker of AKI and a predictor of AKI in different diseases like cardiovascular disease, liver disease, and renal disease." (PMID 38975470, 2024). "Furthermore, IL-6 is positively associated with total bilirubin and INR while being negatively associated with serum albumin and platelets, implying that IL-6 might potentially be used as a marker for the progression of liver disease." (PMID 39071840, 2024). "Liver disease is often accompanied by an inflammatory response, and inflammatory mediators such as TNF-alpha and IL-6 can affect lipid metabolism, leading to elevated lipid levels." (PMID 39678246, 2024). "IL-6, TNF-α, and TGF-β1 are important inflammatory factors in the inflammatory response of the liver and are involved in a variety of liver diseases." (PMID 35629298, 2022). "Patients with acute decompensation during follow-up showed higher baseline levels of IL-6, sFasL, CK18-M65 and–M30 (P<0.01) compared to patients with stably compensated liver disease." (PMID 35176084, 2022). "In Gr.2, IL-6 and MCP-1 were numerically high, and IL-8 and IL-1β were lower, suggesting immunological uniqueness by the staging of the liver disease." (PMID 36232646, 2022). "In the early phase of liver diseases, Kupffer cell-derived proinflammatory cytokines, including CCL2, IL-1β, IL-6, IL-23, and TNF-α, induce the migration of immune cells and HSCs and contribute to the development of a proinflammatory liver microenvironment." (PMID 36380016, 2022). "The proinflammatory cytokines IL-6 and TNF-α activate the transcription factors STAT3 and NF-κB, which if persistently stimulated can aggravate liver disease progression and HCC development." (PMID 32357520, 2020). "Many studies have suggested that various cytokines, such as IL-2, IL-6, IL-8, IL-10, and IL-12 were involved in the progression of HBV-related liver disease and HCC." (PMID 31200663, 2019). "The expression of IL-6, one of the major STAT3-activating cytokines, and is elevated in human liver diseases and HCC32." (PMID 30250040, 2018). "Considerable evidence has accumulated to suggest that the NF-κB signaling pathway contributes to the pathogenesis of liver inflammatory diseases through the activation of TNF-α, IL-6, and IL-1β." (PMID 29849889, 2018). "Serum levels of inflammation related cytokines, including IL-6, 10, and TNF-α, tend to increase with the MELD score, which is related to the severity of liver disease." (PMID 29649247, 2018). "There is evidence supporting an important role of cytokines, including interleukin- (IL-) 1α, IL-6, and tumor necrosis factor (TNF) in various aspects of inflammatory liver diseases." (PMID 26448742, 2015). "Mean IL-6, IL-8, hsCRP, and TNF-α levels were higher among individuals with more advanced liver disease." (PMID 26343741, 2015). "A significantly higher frequency of IL6 and TGF-β double-high patients was detected in CH-C than in other liver diseases." (PMID 24905921, 2014). "Increased circulating levels of IL-6 and TNF-α have been found in animal models and patients with liver disease including HCC." (PMID 24918094, 2014).
liver disease (continued). "Hazard ratios of all-cause, cardiovascular, cancer, and liver mortality stratified by IL-6 tertiles over 15 years of median follow-up (excluding individuals with prevalent CVD, cancer, and liver disease)." (PMID 22514624, 2012). "While TNF alfa, IL-6, and IL-8 (CXCL8) are markers of the innate immune “storm” (neutrophil-related), CXCL9 and CXCL10 reflect the adaptive immune response (Th1/lymphocytic) as well as hemodynamic severity (portal hypertension)." (PMID 41373861, 2025). "LIG not only suppresses HCC malignancy but also blocks tumor-associated macrophage recruitment and M2 polarization by inhibiting YAP/IL-6-driven activation of IL-6R/STAT3 signaling 5, suggesting therapeutic utility even in advanced, transformation-prone liver diseases." (PMID 40860128, 2025). "In liver disease, innate immune cells respond to hepatic insults by activating cell-intrinsic inflammasomes via toll-like receptors and NF-κB, and by releasing pro-inflammatory cytokines (such as IL-1β, IL-18, TNF-α and IL-6)." (PMID 38908436, 2024). "Factors related to the rate of increase in platelets due to PSE were investigated by univariate analysis, and the following were identified: the etiology of liver disease (HCV, PBC, and NASH), splenic embolization ratio, IL-6 change ratio, and PAIgG change ratio." (PMID 36221332, 2022). "Interleukin-6 (IL-6), a pro-inflammatory cytokine, has been shown to upregulate GP73 mRNA and protein levels in HepG2 cells and GP73 serum levels correlated with IL-6 levels in patients with pre-malignant liver disease." (PMID 36139589, 2022). "Moreover, cytokine storm, also known as cytokine release syndrome (CRS), identified CRP, IL-6, LDH, and ferritin promotion, leading to ARDS and liver disorders." (PMID 36531832, 2022). "Importantly, existing studies also show a significant co-existence of increased levels of both IL-6 and TGF-β in patients with liver diseases." (PMID 35127527, 2021). "In the present study, we have shown that high levels of IL-6, IL-10, and TNF-α could be protective against severe S. mansoni hepatic disease." (PMID 29610679, 2018). "These investigations indicated that through IL-6, MHBs have different functions at different HBV infection stages and might play complex roles in liver disease pathogenesis." (PMID 27434097, 2016). "For instance, whereas a significant increase in the production of IL-1β, IL-6, IL-12, and TNFα was observed in chronic alcoholics without liver disease, chronic alcoholics with liver disease who were drinking alcohol showed low production of IL-1β and TNFα." (PMID 25762940, 2015). "The results indicated that IL-6 in concert with TGF-β polarized the local milieu to favor the production of Th17 cells rather than Treg cells, which is in keeping with reports by other investigators on liver diseases other than BA." (PMID 26325187, 2015). "IL-8 levels, along with those for IL-6 and IL-10, are elevated in individuals with alcoholism who have no signs of liver disease." (PMID 26695748, 2015). "IL-10 expression is moderately to highly increased in ALD and, along with that of IL-6 and IL-8, is also upregulated in alcoholic patients without signs of liver disease." (PMID 26695748, 2015). "Parameters of alcoholism, such as the pro-inflammatory cytokine IL-6, were found to decrease from baseline through day 15 in a small sample of 52 alcohol-dependent individuals without liver diseases undergoing alcohol detoxification." (PMID 26343741, 2015). "Interleukin-6 (IL-6) has been reported to protect hepatocyte death, but the role of IL-6 in protecting chronic T cell-induced liver diseases is not clearly defined due to lack of relevant animal models." (PMID 21394214, 2011). "CXE is proven to suppress NO, pro-inflammatory (IL-6, IL-1β, and LDH), and apoptosis genes (Casp-9, Casp-3, and JNK) in APAP-mediated liver cells while increasing the expression of an anti-inflammatory agent (IL-10), which can be a potent target for liver disease treatment." (PMID 40584441, 2025).